INS (insulin)
Diseases named in the same sentence as INS in open-access papers (continued):
Sharing a sentence is not in itself a finding about the gene and the disease.
diabetes (continued). "HOMA-IR is calculated as (FPG × fasting insulin)/405 (normal level, <1.6; insulin resistance, >2.5; according to the Japan Diabetes Society)." (PMID 26132231, 2015). "Insulin glulisine (Apidra®, Sanofi) is a rapid-acting insulin analogue indicated for the treatment of adults, adolescents and children 6 years or older with diabetes mellitus where treatment with insulin is required." (PMID 29632561, 2015). "Diabetes is the most prevalent metabolic disease characterized by hyperglycemia due to primary defects in insulin secretion and/or insulin function." (PMID 26300908, 2015). "Lower levels were associated with greater body weight and waist circumference and with higher insulin dose, especially at longer diabetes durations." (PMID 25950008, 2015). "Current pharmacologic treatment of diabetes relies on two main classes of drugs, insulin mimetics and insulin sensitizers." (PMID 26202599, 2015). "B6 mice, which are considered to be obesity- and diabetes-prone and therefore extensively used in metabolic studies, showed overall lower basal and glucose-stimulated insulin secretion capacity under metabolically unstressed conditions, i.e. on the CD." (PMID 26085100, 2015). "The principal aim of this study was to perform an intra-individual comparison of insulin glargine and NPH insulin with regard to patient reported outcomes such as treatment satisfaction, quality of life, and diabetes-specific emotional distress." (PMID 26055391, 2015). "PU want to be able to add their injected insulin units to the glucose diary, to receive updates with current medical information about diabetes and to use the portal for supporting the diabetes care, like scheduling a clinic visit." (PMID 26086272, 2015). "Diabetes, classified as secondary to pancreatitis, was later diagnosed at the age of 22, and was treated with insulin since the beginning of its discovery." (PMID 25885670, 2015). "In this model of diabetes, pancreatic and extrapancreatic organs are exposed to both direct toxic effect of STZ and to severe hyperglycemia following almost total loss of insulin producing beta cells." (PMID 25893200, 2015). "These cases were suffering from diabetic neuropathy on the background of long-existing diabetes (mean 12.4 years) and insulin use." (PMID 25445838, 2015). "It is important to remember, however, that patients with diabetes on large insulin doses were excluded from these studies." (PMID 28702223, 2015). "HRT also improved glucose control in women with preexisting diabetes, and E2 given in a moderate dose (0.625 mg) increased insulin sensitivity; however, higher doses (1.25 mg) or progestins cotreatment attenuated this benefit." (PMID 25883987, 2015). "Melatonin seems to improve insulin action restoring the endogenous rhythm of body temperature after long-term diabetes." (PMID 25960780, 2015). "In those with newly treated diabetes, the majority were prescribed metformin, with smaller percentages prescribed insulin and other oral agents." (PMID 26335938, 2015). "While the consequences of insulin overdose are rarely fatal, hypoglycemic events are unpleasant and medication-related problems contribute to unscheduled care use by people with diabetes." (PMID 25943590, 2015). "The insulin duration ranges from 2 h to 8 h; diabetes patient should choose a reasonable duration time." (PMID 26550021, 2015). "Diabetes mellitus is a common metabolic disorder characterized by chronic hyperglycemia, as a result from defects in insulin production and insulin action." (PMID 26294929, 2015). "Diabetes has traditionally been divided into T1D (onset in children, clear evidence of autoimmune destruction of the insulin-secreting β cells) and T2D, (onset at 35–40 years, β cells still competent, and no obvious signs of autoimmunity)." (PMID 26146464, 2015).
diabetes (continued). "In terms of diabetes management, the foot cases were frequent users of insulin, which is consistent with other studies, and as expected, since poorly controlled foot cases will require insulin treatment." (PMID 25946144, 2015). "Impaired insulin-stimulated muscle glucose uptake (MGU) is a hallmark of insulin resistant states many of which can be induced by inflammation, obesity, diabetes, and vascular dysfunction." (PMID 25986700, 2015). "On the other hand, CPS-1 stimulates pancreatic release of insulin and/or reduces insulin metabolism, so the polysaccharide can treat diabetes." (PMID 25960753, 2015). "T2DM and T2DM + CAD groups were also equal regarding percentage taking insulin and the diabetes control parameters fasting glucose and HbA1c." (PMID 26268997, 2015). "Type 2 diabetes mellitus (T2DM), the most common form of diabetes mellitus, is a metabolic disorder characterized by hyperglycemia resulting from peripheral insulin resistance with defective insulin secretion." (PMID 26783411, 2015). "Diabetes Mellitus (DM) is a metabolic disorder that results from beta cell dysfunction and/or the failure of insulin to exert its biological influence at the level of the muscle or the liver, thus leading to chronic hyperglycaemia." (PMID 26193295, 2015). "All 106 patients with a history of diabetes were treated with some kind of diabetes therapy, with 34 % being on insulin therapy." (PMID 25964053, 2015). "There were no significant sex differences, age, creatinine, duration of diabetes, or daily insulin dose." (PMID 25803807, 2015). "In a similar study, folate (FA) coupled PEG-PLGA nanoparticles were used to encapsulate insulin by solvent evaporation method and showed that once-daily administration would be sufficient to control diabetes for at least 24 h." (PMID 26498972, 2015). "More recently, in a model of murine STZ-induced diabetes, blood glucose and serum insulin levels were normalized following concomitant transplantation of BM cells with syngeneic or semiallogeneic MSCs, via a single injection." (PMID 26576437, 2015). "From this, we ascertained that 18 % of patients admitted to our hospital have diabetes, and that 85 % of these patients receive subcutaneous insulin while hospitalized (the remainder receive insulin via intravenous infusion)." (PMID 26429339, 2015). "Type 1 diabetes mellitus (T1DM) is the result of a complex autoimmune response that destroys insulin-producing β-cells in the pancreas." (PMID 26556589, 2015). "Although the underlying mechanisms for the development of human T1D (autoimmune disease) are completely different from T2D, insulin signaling pathway, glucose levels, and energy storage components are involved in both types of diabetes." (PMID 26337083, 2015). "As such, C57BL6/J male mice were fed a high-fat diet (HFD) for 21 weeks to induce diabetes and then received 4 weeks of daily insulin glargine or sham subcutaneous injections." (PMID 25633992, 2015). "The hypoglycemic effect of trivalent chromium was reported under insulin-deficient conditions and exhibited significant antidiabetic potential in STZ-induced diabetes in rats." (PMID 25652875, 2015). "Rosiglitazone was released by GlaxoSmithKline in 1999 for diabetes patients as an insulin sensitizer." (PMID 26659605, 2015). "Hypoglycaemia is a common side effect of insulin therapy and presents a barrier to diabetes management, however, limited data exist on the real-world frequency of events." (PMID 25421366, 2015). "Previous studies have suggested that abnormal activation of GSK3β and decreased levels of p-GSK3β can depress glycogen synthesis and inhibit the insulin signaling pathway, which contributes to in the induction of insulin resistance in diabetes mellitus." (PMID 26296196, 2015).
diabetes (continued). "Eight weeks after induction of diabetes, icariside II was administered by gastric lavage once a day (5 mg/kg) for 6 weeks; and 2–6 units of intermediate-acting insulin were given to maintain normal glycemia for 6 weeks." (PMID 25781208, 2015). "Nowadays, insulin and different oral hypoglycemic drugs are commercially available; however diabetes mellitus still remains a major health concern for humans." (PMID 25995968, 2015). "In diabetes, due to defects in the production of insulin or its action, blood glucose levels become elevated." (PMID 26347893, 2015). "Although the insulin therapy has improved the lives of all people affected by diabetes, it is still one of the most challenging health problems worldwide, with high incidences of many complications." (PMID 25658748, 2015). "In order to study the effect of a GLP-1 analogue in patients with poorly controlled type 2 diabetes mellitus, we first optimized insulin therapy in this study." (PMID 25785276, 2015). "The liver is sensitive to insulin in modulating glucose metabolism, and thus, can be severely affected by diabetes." (PMID 26176625, 2015). "T2DM, the predominant type of diabetes, is characterized by impaired peripheral insulin sensitivity and glucose tolerance, ultimately leading to β-cell failure and diminution or dedifferentiation." (PMID 26510947, 2015). "Carbohydrate counting and insulin dose calculations based on carbohydrates and blood sugars are integral to intensive insulin management of type 1 diabetes mellitus (T1DM)." (PMID 26636015, 2015). "We also analyzed the relationship between coffee intake and glucose/insulin metabolism in participants with previously diagnosed diabetes during a standardized meal test." (PMID 25978631, 2015). "The present study detected the effect of berberine on the glucose and insulin secretion in diabetes and the results showed that berberine effectively reduced the glucose level and body weight in diabetic hamsters." (PMID 25705654, 2015). "This is unfortunate, as both basal and premixed insulin have a definite role to play in the management of diabetes, in all ethnic groups." (PMID 25874190, 2015). "Diabetes mellitus is a group of pathogenically heterogeneous diseases sharing the trait of absolute or relative insufficiency of insulin effect." (PMID 26426397, 2015). "Furthermore, our finding of a stronger association between adiponectin and insulin sensitivity among young healthy Mexican Americans compared to non-Latino whites suggests that adiponectin may be a stronger contributor to diabetes risk in the former population." (PMID 26703682, 2015). "Diabetes mellitus (DM) is a metabolic disorder caused by the chronically high blood glucose levels in the body, which may be the consequence of defect in insulin secretion, insulin action or combination of both." (PMID 25969822, 2015). "Deterioration in diabetes control is often experienced in adolescence due to myriad factors, including increased insulin requirements related to growth and other hormonal changes." (PMID 25791276, 2015). "Cohort study based on data from the Swedish National Diabetes Register, including 5077 insulin-naïve men and women with type 2 diabetes, resident in a distinct geographical region of Sweden." (PMID 28702235, 2015). "Reduction of BMPR1A signaling mediated by Cre recombinase under the control of the rat insulin promoter (RIP) was shown to induce diabetes from 2–3 months of age." (PMID 26187948, 2015). "Induction of Type I diabetes was confirmed by measuring insulin and blood glucose levels after 28 days of diabetes." (PMID 25974252, 2015). "This prediction ofLT10 peptide as a novel putative IDE-inhibitor suggests its possible role in anti-diabetic treatment since IDE- inhibitors are known to assist treatment of Diabetes mellitus by enhancing insulin signalling." (PMID 25816209, 2015).
diabetes (continued). "Before the discovery of insulin and its clinical use to treat diabetes mellitus, oral administration of sodium vanadate was reported for the treatment of DM in humans." (PMID 26783461, 2015). "Diabetes was diagnosed before transplantation in 34 (64%) of the CF patients, of whom 27 patients (79%) already used insulin at screening." (PMID 26698308, 2015). "The high activity of GPx1 can interfere with insulin signaling, which is critical to the regulation of glucose levels and the prevention of diabetes." (PMID 25880386, 2015). "Oral hypoglycemic drugs were the most common drugs for treatment of diabetes in G1 (66.7%) and insulin in G2 (50.0%)." (PMID 25993052, 2015). "Type 1 diabetes mellitus (T1DM) is an autoimmune disease leading to the destruction of the insulin-producing pancreatic beta cells in the islets of Langerhans." (PMID 25960780, 2015). "A systematic review and meta-analysis of 11 trials compared the effects of treatment with regular insulin versus short-acting insulin analogues over HRQoL of patients with diabetes." (PMID 26110026, 2015). "The insulin signaling pathway, the top pathway in the second module, plays important roles in many complex diseases such as diabetes, obesity, and neurological disorders." (PMID 26083494, 2015). "Recombinant insulin and its analogs represent one of the most important classes of therapeutics for diabetes, and have been prescribed to nearly one third of U.S. anti-diabetic drug users in the past decade." (PMID 25799496, 2015). "We previously identified compensatory changes in insulin secretion among adults before diabetes diagnosis using this approach." (PMID 25431266, 2015). "This approval was based on results from an NIH open-label, single-arm study of 48 patients with congenital, or acquired generalized lipodystrophy, who also had diabetes mellitus, hypertriglyceridemia, and/or elevated levels of fasting insulin." (PMID 25885670, 2015). "The type 2 diabetic db/db mice exhibited typical symptoms of diabetes, including increased levels of blood glucose, hyperinsulinemia, decreased insulin sensitivity index." (PMID 26666849, 2015). "Impairment in overall insulin signalling with respect to both insulin secretion and insulin action ultimately affects the blood glucose level resulting in a condition referred to as Diabetes mellitus." (PMID 25816209, 2015). "Diabetes-associated risk factors, including FBS, insulin, and HOMA-IR were strongly associated with C14:0 and C18:3n6, a product generated by D6D." (PMID 26497880, 2015). "The diagnosis of type 1 diabetes mellitus was confirmed by the detection of autoantibodies against glutamic acid decarboxylase 65, islet cell antibodies, and anti-insulin autoantibodies." (PMID 25821607, 2015). "Patients being considered for insulin treatment are usually those with an advanced stage of diabetes (median duration 6.6 vs. 4.6 years in DiaRegis) and higher blood glucose levels (HbA1c 8.1 vs. 7.3%), with corresponding changes in FPG and PPG." (PMID 25645672, 2015). "Embryonic stem cells are potential sources for insulin producing β cell replacement and these transplantations have been proposed as a potential treatment for diabetes." (PMID 26075247, 2015). "The current world-wide epidemic of diabetes has prompted attempts to generate new sources of insulin-producing cells for cell replacement therapy." (PMID 25706282, 2015). "One of the current drugs for diabetes, pioglitazone, is able to improve insulin sensitivity by stimulating PPARγ signaling in Tregs, leading to increased VAT Treg cell frequency." (PMID 26146464, 2015). "Taken together, calpains, especially calpain-10 and −3, and μ-calpain play an important role in the pathogenesis of diabetes, such as insulin resistance, insulin secretion, glycogen synthesis, glucose transporter turnover and ED." (PMID 26120352, 2015).
diabetes (continued). "The development of diabetes is the result of β-cell destruction (insulin-production) in the pancreatic islets by an inflammatory process that can be generated by oxidative stress." (PMID 26783951, 2015). "Even the United Kingdom Prospective Diabetes study over 6 years of conventional treatment for type 2 diabetes has shown that insulin sensitivity, the reciprocal of insulin resistance being constant with 62, 60 and 62 % at 0, 1 and 6 years." (PMID 26521236, 2015). "Alloxan, a well-known diabetogenic drug, was used to induce a type-1 form of diabetes in rats, characterized by low insulin levels and hyperglycemia." (PMID 25695047, 2015). "Patients meeting inclusion criteria were offered the opportunity to manage their own basal-bolus insulin with support from a diabetes nurse practitioner." (PMID 26429339, 2015). "After reviewing relevant articles, we focused on the following parameters: age, gender, diabetes duration, insulin use, baseline BMI, and levels of fasting glucose, HbA1c, and C-peptide." (PMID 25103403, 2015). "Mortality from acute complications of diabetes in Brazil has declined markedly in parallel with the implementation of a national health system providing access to insulin and organization of health care." (PMID 26259708, 2015). "Patients with diabetes were taking a wide range and combinations of metabolically active drugs, such as oral hypoglycaemic drugs, insulin and statins." (PMID 26049400, 2015). "While the general concept is that breastfeeding is protective and should be promoted, some studies report increased levels of insulin and glucose in breast milk of women with diabetes, possibly increasing risks to the children." (PMID 26361494, 2015). "Many European countries previously imposed a blanket ban on most drivers with insulin-treated diabetes, particularly to drive large goods vehicles or passenger carrying vehicles." (PMID 28702227, 2015). "In the poorly controlled patients with type 2 diabetes mellitus (DM), insulin therapy is the treatment of choice to control glucose levels on target." (PMID 26607841, 2015). "Diabetes mellitus (DM) is a metabolic disorder resulting from a defect in insulin secretion, insulin action, or both." (PMID 25734015, 2015). "Insulin therapy consisted of basal, prandial and correction insulin according to nutritional support, glycemic control and outpatient treatment for diabetes." (PMID 26697118, 2015). "Diabetes mellitus is a chronic disease that results from the body's inability to sufficiently produce and/or properly use insulin." (PMID 26221177, 2015). "Other drugs used in management of diabetes mellitus (other oral drugs and insulin) were largely unavailable." (PMID 26399634, 2015). "Intervention group patients were significantly more likely to have seen a dietician and dentist and slightly more likely to have seen a diabetes educator, be taking insulin and having influenza vaccination." (PMID 25884300, 2015). "Type 2 diabetes mellitus (T2DM) is a metabolic disease defined by the presence of chronic hyperglycemia due to a simultaneous development of insulin resistance and a relative defect of the pancreatic islet to secrete insulin." (PMID 25808148, 2015). "It exerts stimulatory effects on insulin (and c-peptide) secretion, raising the possibility of its use in the treatment of diabetes." (PMID 26617516, 2015). "All of the patients were under treatment for diabetes, specifically by therapy with insulin, oral anti-hyperglycemic agents or both." (PMID 26167910, 2015). "Cox models were used, considering the following independent variables: age, sex, diabetes type, diabetes duration, body mass index, smoking, insulin use, and area of residence." (PMID 26171401, 2015). "Remarkably, females were more prone to developing diabetes as a result of lower insulin secretion as compared to their male counterparts." (PMID 25726699, 2015).